TIMP4 (TIMP metallopeptidase inhibitor 4)
Diseases named in the same sentence as TIMP4 in open-access papers (continued):
Sharing a sentence is not in itself a finding about the gene and the disease.
delirium (1 paper, 2024). A disorder characterized by confusion; inattentiveness; disorientation; illusions; hallucinations; agitation; and in some instances autonomic nervous system overactivity. "Low levels of TIMP-4 appear to be directly associated with delirium, and the role of this marker in delirium pathophysiology should be further explored." (PMID 38937571, 2024).
depression (1 paper, 2024). "However, we conducted a cross-analysis of potential sites associated with depression and schizophrenia, which revealed four intersecting sites: BTN3A1, CYP21A2, PSMB4, and TIMP4." (PMID 38637810, 2024). "We have identified shared comorbidity loci between schizophrenia and depression, including BTN3A1, PSMB4, and TIMP4." (PMID 38637810, 2024). "Shared comorbidity loci between depression and schizophrenia included BTN3A1, PSMB4, and TIMP4." (PMID 38637810, 2024).
disc degeneration (1 paper, 2024). "Although these catabolic factors were counteracted by even higher and increasing expression levels of their natural endogeneous inhibitors such as TIMP-1, TIMP-2, TIMP-3 and TIMP-4, we recoded declining levels of aggrecan and collagen II with increased severity of disc degeneration." (PMID 39286594, 2024).
emphysema (1 paper, 2016). "We found significantly increased TIMP-2 and TIMP-4 in COPD subjects and also found that TIMP-4 had positive associations with several emphysema sub-types." (PMID 27460105, 2016).
endometrial cancer (1 paper, 2024). Primary or metastatic malignant neoplasm involving the endometrium (mucous membrane that lines the endometrial cavity). "Current research shows that endometrial cancer expresses more TIMPs (Tissue Inhibitors of Metalloproteinases), including MMP26 (Matrix Metalloproteinase 26), TIMP-3 (Tissue Inhibitor of Metalloproteinases-3), and TIMP-4(Tissue Inhibitor of Metalloproteinases-4)." (PMID 38782818, 2024).
endometrial tumor (1 paper, 2023). "In EC, TIMP4 transcript levels were lower, whereas high TIMP4 protein expression was detected in endometrial tumor tissue in correlation with myometrial invasion, suggesting a key role in endometrial tumor progression." (PMID 37313172, 2023).
endometriosis (1 paper, 2023). The growth of functional endometrial tissue in anatomic sites outside the uterine body. "Although there has been no report about the relationship between endometriosis and TIMP-4, the increase in TIMP-4 expression by treatment with dienogest may be related to the anti-endometriotic effect of dienogest." (PMID 36752987, 2023).
esophageal squamous cell carcinoma (1 paper, 2020). Esophageal squamous cell carcinoma (ESCC) is a type of esophageal carcinoma (EC) that can affect any part of the esophagus, but is usually located in the upper or middle third. "In esophageal squamous cell carcinoma (ESCC), miR-21, miR-130b, and miR-301 downregulate their target mRNAs, which include BMP6, PDCD4, and TIMP4, and induces EMT." (PMID 32967226, 2020).
fibrosarcoma (1 paper, 2018). A malignant mesenchymal fibroblastic neoplasm affecting the soft tissue and bone. "mRNA expression of TIMPs in matrix embedded fibrosarcoma cells demonstrates that cell-density significantly increased TIMP3 and TIMP4 expression but did not impact TIMP1 or TIMP2." (PMID 30220965, 2018).
gastric cancer (1 paper, 2017). A primary or metastatic malignant neoplasm involving the stomach. "Ideally, we should evaluate the gene only after determining the roles of MMPs’ inhibitors, such as TIMP-1, TIMP-2, TIMP-3, and TIMP-4, in the development of gastric cancer." (PMID 29228747, 2017).
Glucose intolerance (1 paper, 2017). Glucose intolerance (GI) can be defined as dysglycemia that comprises both prediabetes and diabetes. "However, after 12 weeks of HFD, Timp4−/− and WT mice exhibited the same degree of glucose intolerance indicating that the reduced adiposity in Timp4−/−-HFD mice did not exert protection against glucose intolerance." (PMID 28740132, 2017).
hemorrhage (1 paper, 2024). Loss of blood from the vascular compartment to the exterior or into nonvascular body space as a result of rupture or severance of the blood vessels. "Moreover, mean CSF TIMP4 levels were lower in CAA patients who had experienced a symptomatic hemorrhage compared to CAA patients who did not (2.13 ± 0.24 vs. 3.57 ± 0.24 ng/ml, p = 0.007)." (PMID 38915119, 2024).
hepatocellular carcinoma (1 paper, 2019). A malignant tumor that arises from hepatocytes. "Similar to that observed in the present study, down-regulated expression of aquaporin, AQP7 gene belonging to water channel family, TIMP4 belonging to mettalloproteinases inhibitor family member was also reported in breast and hepatocellular carcinoma at transcript level." (PMID 31292488, 2019).
hepatopathy (1 paper, 2013). "We then aimed to directly compare the diagnostic performance of TIMP-4, Endoglin and TE as novel diagnostic markers for CFLD to clinical markers of hepatopathy." (PMID 23516586, 2013).
hip osteoarthritis (1 paper, 2019). "(2010) reported that that TIMP4 was significantly down-regulated in the bone of primary hip osteoarthritis, consistent with a role as a pivotal regulator of osteoblast expression." (PMID 30697482, 2019).
Hypercholesterolemia (1 paper, 2017). An increased concentration of cholesterol in the blood. "In addition, Timp4−/−-HFD mice do not exhibit hypercholesterolemia mainly due to lower LDL-cholesterol levels, suggesting a possible role of TIMP4 in cholesterol metabolism." (PMID 28740132, 2017).
Hyperglycemia (1 paper, 2017). An increased concentration of glucose in the blood. "This suggests that hyperglycemia affects the physiological production of TIMP-4 following increased MMP-2 synthesis." (PMID 28770228, 2017).
hyperhomocysteinemia (1 paper, 2023). A serious metabolic condition caused by mutations in the MTHFR gene, medications, or nutritional deficiency. "Folate availability has been shown to alter plasma homocysteine, and hyperhomocysteinemia might induce an imbalance between the activity of matrix metalloproteinase 9 and TIMP4." (PMID 37640106, 2023).
IgA nephropathy (1 paper, 2026). "Transcriptomic-wide MR identified candidate genes across GN subtypes: RECQL, BRSK2, and MGP in acute GN; AFM, CFHR5, and EPHB2 in chronic GN; IL6R, MBL2, and PRSS3 in IgA nephropathy; and TIMP4, HCK, and PEAR1 in membranous nephropathy." (PMID 41990104, 2026).
infarction (1 paper, 2022). A localised pathological necrosis of tissue resulting from obstruction of the blood supply usually by a thrombus, an embolus, or vascular torsion. "TIMP-4 is strongly expressed in the cardiovascular system under physiological conditions, and numerous studies showed a relative reduction of TIMP-4 expression level after infarction." (PMID 36082193, 2022).
inflammatory bowel disease (1 paper, 2008). A spectrum of small and large bowel inflammatory diseases of unknown etiology. "Since chronic inflammation is associated with tissue remodeling in inflammatory bowel disease (IBD), we evaluated serum TIMP-1 and TIMP-4 levels in IBD patients, in comparison with healthy controls (HC)." (PMID 19036126, 2008).
joint diseases (1 paper, 2025). "However, the role of TIMP4 in joint diseases remains poorly understood." (PMID 40291774, 2025).
Kawasaki disease (1 paper, 2019). A rare inflammatory disease characterized by an acute febrile, systemic, self-limiting, medium-vessel vasculitis primarily affecting children. "In a study of Korean children, an association of rs3755724 of TIMP4 with the development of Kawasaki disease with coronary artery lesions was identified." (PMID 30697482, 2019).
keratoconus (1 paper, 2024). A degenerative, structural disorder of the eye, characterized by a cone-shaped protrusion of the cornea. "High diagnostic sensitivity and specificity values of TIMP-1 and TIMP-2 and high diagnostic specificity values of TIMP-3 and TIMP-4 in relation to keratoconus were demonstrated, which confirms their strong role in the etiopathogenesis of this disease, especially when they all interact together." (PMID 38398480, 2024). "TIMP-1, TIMP-2, TIMP-3, and TIMP-4 values were analyzed for their usefulness as potential predictors of keratoconus." (PMID 38398480, 2024). "The aim of the study was to determine the concentration of the TIMPs TIMP-1, TIMP-2, TIMP-3, and TIMP-4 in the blood serum samples of patients with keratoconus compared to the control group." (PMID 38398480, 2024). "Due to the lack of research on TIMP-4 in keratoconus, further development of the topic in this direction is needed." (PMID 38398480, 2024).
lipidosis (1 paper, 2022). "Beyond our hypothesis, effects of treatment were clearly multifactorial and, in part, appeared to be associated with an increased expansion of VAT involving the modulation of growth factors such as IGF1 and FGF1, ECM organization through TIMP4, and lipidosis." (PMID 35737302, 2022).
liver cirrhosis (1 paper, 2013). "As a proof of principle in HCV patients, we also provide evidence that TIMP-4 serum levels show highest values in patients with complete liver cirrhosis." (PMID 23516586, 2013). "Similar to our observations for TIMP-4, Endoglin serum levels were highest in HCV patients with complete liver cirrhosis, suggesting a close relation to hepatic staging." (PMID 23516586, 2013).
liver disease (1 paper, 2013). "Further, in the CF patient cohort TIMP-4 exhibited a high accuracy for the detection of liver disease and when used in combination with transient elastography for CFLD diagnosis, the diagnostic sensitivity and negative prediction was considerably improved." (PMID 23516586, 2013). "CF Patients with CFLD diagnosed according to recent guidelines exhibited significantly increased serum levels of TIMP-4 and Endoglin compared to those without liver disease." (PMID 23516586, 2013). "Using this approach, our results identify TIMP-4 and Endoglin as novel and promising serum markers of liver disease in CF patients that hold the potential to facilitate the non-invasive assessment of CFLD." (PMID 23516586, 2013).
lung carcinoma (1 paper, 2016). "In most of the lung cancer cell lines there was frequent methylation of the CpG islands for TIMP4 (64%)." (PMID 27396717, 2016).
malignant glioma (1 paper, 2022). A grade III or grade IV glioma arising from the central nervous system. "Further, our finding of a positive and negative association with TIMP1 and TIMP4 expression, respectively, is in line with a previous study comparing their mRNA and protein expression in normal human brain and malignant gliomas." (PMID 35480116, 2022).
melasma (1 paper, 2022). "There was an increase in MMP1 gene expression and a decrease in collagen IV, VII (COL4A1, COL7A1), and TIMP4 expression in fibroblasts isolated from melasma skin." (PMID 35840442, 2022). "TheWNT3A, EDN3, ESR2, PTG2, MMP1, and SOD2 genes were up-regulated, whereas the COL4A1, CSF2, DKK3, COL7A1, TIMP4, CCL2, and CDH11 genes were down-regulated in melasma skin fibroblasts when compared to the ones from adjacent healthy skin." (PMID 35840442, 2022).
meningioma (1 paper, 2024). A generally slow growing tumor attached to the dura mater. "Significant fold changes were found in MMP10, TIMP1, and TIMP4 in meningioma patients." (PMID 38474106, 2024).
migraine (1 paper, 2018). "TIMP Metallopeptidase Inhibitor 4 (Timp4), an inhibitor of the matrix metalloproteinases, has been linked to the pathophysiology of migraine." (PMID 30618656, 2018).
myocardial tumors (1 paper, 2008). "It has also been suggested that the increased TIMP-4 expression in normal heart tissue could explain why myocardial tumors are so rare." (PMID 19036126, 2008).
myocarditis (1 paper, 2021). Myocarditis is a condition that is characterized by inflammation of the heart muscle (myocardium). "Many studies have reported the expression level of TIMP-4 is down-regulated in CVB3-induced myocarditis, which is in contrast with our result." (PMID 34452454, 2021).
neuropathic pain (1 paper, 2016). Chronic pain caused by damage to nerve fibers. "Of the 47 investigated proteins, 21 (cathepsin S, CCL2, CCL4, CCL16, CFIII, CXCL5, cystatin B, E-Selectin, Fas/TNFRSF6, follistatin, GDF-15, GH, ICAM1, IL8, KLK5, MMP2, MMP9, P-Selectin, sortilin, TIMP4 and VEGF) were detectable by multiplex SP-PLA in ≥ 95% of the neuropathic pain patient samples." (PMID 26914813, 2016).
oral cancer (1 paper, 2015). "Querying the TCGA HNSCC dataset we identified 8 potential mRNA targets (ESM1, KLF4, IL8, CCL20, IL24, CCNA1, TIMP4 and MMP1) from our validated 20 mRNA panel, which were aberrantly expressed in HNSCC and controlled by CELF1 in oral cancer cells." (PMID 26498364, 2015).
papillary thyroid carcinoma (1 paper, 2022). "Recent research indicated that Angiopoietin-1 played a role in lymph node metastasis and invasiveness of papillary thyroid carcinoma TIMPs, which comprise a family of four protease inhibitors: TIMP1, TIMP2, TIMP3, and TIMP4." (PMID 36672532, 2022).
primary open angle glaucoma (1 paper, 2013). "TIMP4 levels were higher in both glaucoma groups (POAG and PXG) when compared to controls (p = 0.001)." (PMID 24498922, 2013). "TIMP4, as a potential inhibitor of MMP activity, could be implicated in ECM homeostasis disorders in glaucoma." (PMID 24498922, 2013). "Thus, besides all other possible TIMP4 properties, the increased levels of this inhibitor may contribute to the altered balance of TIMPs and MMPs in the aqueous humor of glaucoma patients." (PMID 24498922, 2013). "Our results may suggest an important link between glaucoma and TIMP4 action." (PMID 24498922, 2013).
prostate tumours (1 paper, 2021). "In bladder and prostate tumours, TIMP4 is downregulated by chemokine (C-X-C motif) ligand 1 (CXCL1) as an intermediate link to maintain tumour growth." (PMID 34781885, 2021).
rheumatic disorder (1 paper, 2024). Inflammatory and degenerative diseases of connective tissue structures, such as arthritis. "We found that 11 proteins had a significant association with rheumatic disorders with Bonferroni correction (eTable 13 in Supplement 1), namely, interleukin-27, ICAM5, LMAN2L with JIA; TIMP4 with SSc; and 6 proteins with RA, and 4 proteins with SLE." (PMID 39729320, 2024).
rheumatoid arthritis (1 paper, 2025). A chronic, systemic autoimmune disorder characterized by inflammation in the synovial membranes and articular surfaces. "The current study was designed to explore the clinical significance of serum tissue inhibitor of metalloproteinase 4 (TIMP4) levels in rheumatoid arthritis (RA)." (PMID 40291774, 2025).
Sepsis (1 paper, 2025). Sepsis is defined as life-threatening organ dysfunction caused by a dysregulated host response to infection. "Elevated blood serum concentrations of MMP9, MMP2, and TIMP4 are associated with a progressive course of NEC with sepsis." (PMID 40303487, 2025).
steatosis (1 paper, 2025). Increased lipid within the cytoplasm of cells. "Studies on TIMP4-deficient mice fed a high-fat diet demonstrated impaired fat absorption and reduced adipocyte fat accumulation, fibrosis, and steatosis levels." (PMID 40922984, 2025).
Stroke (1 paper, 2019). Sudden impairment of blood flow to a part of the brain due to occlusion or rupture of an artery to the brain. "However, we cannot exclude that the increasing expression of Timp-2, Timp-3 and Timp-4 mRNA also facilitates brain repair after a stroke by increasing cell proliferation and/or differentiation." (PMID 30062663, 2019).
tendinopathy (1 paper, 2023). "Evidence on TIMPs showed that TIMP-1 expression is briefly augmented (compensation) after acute tendon tear and reduced in tendinopathy, whereas TIMP-2, TIMP-3, and TIMP-4 are downregulated in both tendinopathy and tears." (PMID 36830637, 2023).
triple-negative breast carcinoma (1 paper, 2022). An invasive breast carcinoma which is negative for expression of estrogen receptor (ER), progesterone receptor (PR), and human epidermal growth factor receptor 2 (HER2). "Extracellular TIMP4 is involved in promoting the activation of the PI3K/AKT/mTOR pathway and promoting tumor metastasis, and is a prognostic and predictive marker for triple-negative breast cancer." (PMID 35847900, 2022).
tuberculosis (1 paper, 2009). A chronic, recurrent infection caused by the bacterium Mycobacterium tuberculosis. "Of note MMP-3, -8, -9 and TIMP-1 fell and TIMP-4 rose significantly over the course of 9 months anti-tuberculosis treatment." (PMID 19789647, 2009).
type A aortic dissections (1 paper, 2023). "TIMPs inhibit MMPs, and a previous gene expression profiling study showed decreased TIMP4 in aortic specimens of patients with type A aortic dissections, which would result in elevated MMP levels and elastin and collagen degradation in the ascending aortic wall." (PMID 37958625, 2023).
vascular dementia (1 paper, 2024). A degenerative vascular disorder affecting the brain. "Tissue inhibitor of matrix metalloproteinases 4 (TIMP4) is associated with cardiovascular functioning and disease and has been linked to vascular dementia." (PMID 38915119, 2024). "Increased plasma levels of TIMP4 have also been linked to vascular dementia." (PMID 38915119, 2024). "On the other hand, another study demonstrated lower levels of plasma TIMP4 in patients with AD (probably many with CAA) versus patients with vascular dementia, leaving the exact relationship between vascular damage in AD and altered TIMP4 levels somewhat unclear." (PMID 38915119, 2024). "Interestingly, one study previously showed that increased plasma TIMP4 levels are associated with vascular dementia but not with non-vascular dementia." (PMID 38915119, 2024).